B4GALT3 (beta-1,4-galactosyltransferase 3)
Description:
Responsible for the synthesis of complex-type N-linked oligosaccharides in many glycoproteins as well as the carbohydrate moieties of glycolipids.
Synonyms: Beta4Gal-T3
Tractability: Antibody: UniProt predicts a signal peptide or a membrane-spanning region. PROTAC: ubiquitination databases record sites on it; its protein half-life has been measured.
Gene: Protein-coding gene on chromosome 1 (161,171,306 to 161,178,652, reverse strand). Ensembl gene ENSG00000158850.
Subcellular location: Golgi apparatus, Golgi stack membrane
Subcellular location (Human Protein Atlas): Golgi apparatus; Cytosol
Pathways (Reactome):
Metabolism: Keratan sulfate biosynthesis
Metabolism of proteins: N-Glycan antennae elongation
Gene Ontology:
Molecular function: beta-N-acetylglucosaminylglycopeptide beta-1,4-galactosyltransferase activity; galactosyltransferase activity; N-acetyllactosamine synthase activity; glycosyltransferase activity
Biological process: glucosylceramide metabolic process; carbohydrate metabolic process
Cellular component: extracellular exosome; Golgi apparatus; Golgi membrane; Golgi cisterna membrane
Genetic constraint (gnomAD): Loss-of-function variants: 29 observed, 42.74 expected, observed/expected ratio (o/e) 0.68, 90% interval 0.5 to 0.93. The upper end of that interval is the gene's LOEUF score, 0.93, which puts it in group 3 of 6, group 1 being the genes least tolerant of losing a copy. Missense variants: 390 observed, 550.38 expected, observed/expected ratio (o/e) 0.71, 90% interval 0.65 to 0.77. Synonymous variants: 182 observed, 215.67 expected, observed/expected ratio (o/e) 0.84, 90% interval 0.75 to 0.95.
Homologues: Orthologues: chimpanzee B4GALT3 (99% identical), macaque B4GALT3 (99% identical), dog B4GALT3 (98% identical), guinea pig B4GALT3 (98% identical), rabbit B4GALT3 (97% identical), mouse B4galt3 (97% identical), pig B4GALT3 (96% identical), rat B4galt3 (96% identical), tropical clawed frog b4galt3 (66% identical), zebrafish b4galt3 (59% identical), Caenorhabditis elegans bre-4 (35% identical), Drosophila melanogaster beta4GalNAcTA (29% identical). Paralogues in human: B4GALT1 (43% identical), B4GALT4 (41% identical), B4GALT2 (41% identical), B4GALT5 (34% identical), B4GALT6 (34% identical), B4GALT7 (24% identical).